NDUFB4 (NADH:ubiquinone oxidoreductase subunit B4)
Description:
Accessory subunit of the mitochondrial membrane respiratory chain NADH dehydrogenase (Complex I), that is believed not to be involved in catalysis. Complex I functions in the transfer of electrons from NADH to the respiratory chain. The immediate electron acceptor for the enzyme is believed to be ubiquinone.
Synonyms: CI-B15; B15
Tractability: Small molecule: an approved drug acts on it; a structure with a bound ligand is known. Antibody: UniProt predicts a signal peptide or a membrane-spanning region. PROTAC: ubiquitination databases record sites on it; its protein half-life has been measured.
Gene: Protein-coding gene on chromosome 3 (120,596,303 to 120,602,507, forward strand). Ensembl gene ENSG00000065518.
Subcellular location: Mitochondrion inner membrane
Subcellular location (Human Protein Atlas): Mitochondria; Nuclear membrane; Nucleoplasm; Principal piece
Pathways (Reactome):
Metabolism: Complex I biogenesis; Respiratory electron transport
Gene Ontology:
Molecular function: NADH dehydrogenase (ubiquinone) activity
Biological process: aerobic respiration; mitochondrial electron transport, NADH to ubiquinone; proton motive force-driven mitochondrial ATP synthesis; proton transmembrane transport
Cellular component: mitochondrial inner membrane; mitochondrion; respiratory chain complex I
Genetic constraint (gnomAD): Loss-of-function variants: 11 observed, 16.07 expected, observed/expected ratio (o/e) 0.68, 90% interval 0.43 to 1.13. The upper end of that interval is the gene's LOEUF score, 1.13, which puts it in group 4 of 6, group 1 being the genes least tolerant of losing a copy. Missense variants: 165 observed, 169.1 expected, observed/expected ratio (o/e) 0.98, 90% interval 0.86 to 1.11. Synonymous variants: 65 observed, 66.69 expected, observed/expected ratio (o/e) 0.97, 90% interval 0.8 to 1.2.
Homologues: Orthologues: chimpanzee NDUFB4 (100% identical), dog NDUFB4 (78% identical), guinea pig NDUFB4 (77% identical), pig NDUFB4 (77% identical), mouse Ndufb4 (74% identical), macaque NDUFB4 (72% identical), rat Ndufb4l3 (72% identical), rabbit NDUFB4 (71% identical), rat LOC120094308 (71% identical), rat Ndufb4l4 (71% identical), rat Ndufb4l1 (69% identical), rat Ndufb4 (64% identical), and 4 more.
Diseases named in the same sentence as NDUFB4 in open-access papers:
NDUFB4 is named in the same sentence as 16 diseases in open-access papers, as found by Europe PMC text mining. Sharing a sentence is not in itself a finding about the gene and the disease. The quoted sentences say what the papers report.
Alzheimer disease (2 papers, 2018 to 2019). A progressive, neurodegenerative disease characterized by loss of function and death of nerve cells in several areas of the brain leading to loss of cognitive function such as memory and language. "Notably, we identified that CO therapy decreased the expression of genes encoding ETC complex I genes: NDUFB4, NDUFS2, NDUFAB1, NDUFA6, NDUFB9, also enriched in Parkinson’s, Huntington’s and Alzheimer disease pathways." (PMID 31615996, 2019).
ovarian carcinoma (2 papers, 2025). A malignant neoplasm originating from the surface ovarian epithelium. "Altogether, we have demonstrated that Metformin potentiates apoptosis and ferroptosis in ovarian cancer cells under energy stress conditions by targeting the NDUFB4 subunit of mitochondrial complex I, thus laying the groundwork for clinical testing." (PMID 39937004, 2025).
colorectal cancer (1 paper, 2024). A primary or metastatic malignant neoplasm that affects the colon or rectum. "NDUFB4 was associated with poor prognosis of colorectal cancer and gastric cancer." (PMID 38698303, 2024).
Hypertension (1 paper, 2022). The presence of chronic increased pressure in the systemic arterial system. "Here, in the myocardium of the hypertension-induced HFpEF, we also observed the increased expression of PGC-1a after CANA treatment, which was consistent with the increased expression of the mitochondrial membrane respiratory chain component protein subunit Ndufb4, COX2, Cox4i1, Cox5b, and Cox6a1." (PMID 35370704, 2022).
idiopathic pulmonary hypertension (1 paper, 2024). "Furthermore, the results indicated an increase in the expression of DEGs related to the reactive oxygen species pathway (NDUFB4, PDLIM1, GPX4, and JUNB), and a decrease in the expression of SOD, which has an antioxidant function, in the presence of idiopathic pulmonary hypertension." (PMID 38586587, 2024).
cancer (5 papers, 2019 to 2024). A tumor composed of atypical neoplastic, often pleomorphic cells that invade other tissues. "Recent research evidence has revealed that lncRNA ZFAS1 can encode a small peptide to down-regulate NADH dehydrogenase expression (NDUFA6, NDUFB11 and NDUFB4) to enhance ROS production, thus promoting cancer development." (PMID 34888249, 2021). "Through mapping cancer type-specific in silico KMT2D GI networks, we revealed several SL candidates, namely NDUFB4, MDM2, TUBA1B, and WRN, that encode targets of existing and in-development therapeutics, making them potentially viable drug targets in cancers harbouring KMT2DLOF alterations." (PMID 39578878, 2024). "However, NDUFB4 has been rarely reported upon in human cancers." (PMID 33607292, 2020). "Down-regulate NADH dehydrogenase expression (NDUFA6, NDUFB4, and NDUFB11) to enhance ROS production and thus promote cancer cell migration." (PMID 34888249, 2021). "Function enrichment analysis revealed that gene NDUFB4 and GTF2E1 affect cancer-related functions such as transmembrane transport and transformation factors." (PMID 31998369, 2019). "Therefore, we propose that upregulated ZFAS1 promotes cancer cell migration via elevating cellular ROS production by repressing the expression of NADH dehydrogenases, including NDUFA6, NDUFB4, and NDUFB11." (PMID 31781169, 2019). "Finally, we found that the experimentally validated translated lncRNA ZFSA1 promoted cancer cell migration by elevating cellular ROS production via the expression downregulation of NADH dehydrogenase expression (NDUFA6, NDUFB4, and NDUFB11)." (PMID 31781169, 2019).
tumor (2 papers, 2023 to 2025). "Building on our network result that key gene set 2 is enriched for mitochondrial energy metabolism, the late-stage regulators we identified—UQCR11, NDUFB4, PRDX3, and S100A10—map to pathways that could support or amplify ADSCs-to-tumor bioenergetic coupling." (PMID 41325391, 2025).
infection (1 paper, 2025). The state of being infected such as from the introduction of a foreign agent such as serum, vaccine, antigenic substance or organism. "Leucine-rich alpha-2-glycoprotein 1 and NADH:ubiquinone oxidoreductase subunit B4 are potential biomarkers associated with infection severity." (PMID 40447567, 2025). "We found that NDUFB4, an accessory subunit of complex I, was the most significantly downregulated protein in postoperative IE samples and could reflect severe infection." (PMID 40447567, 2025). "In conclusion, we hypothesize that NDUFB4 might contribute to energy synthesis to resist infection and has emerged as a candidate biomarker for IE, indicating infection severity and clearance dynamics." (PMID 40447567, 2025).
neurodegenerative disease (1 paper, 2025). A disorder of the central nervous system characterized by gradual and progressive loss of neural tissue and neurologic function. "The mitochondrial dysfunction in the neurodegenerative diseases cluster (Cluster 4) comprises 95 genes, including several key mitochondrial protein genes acting as pivotal hub genes, such as Sdhb, Ndufa4, Ndufb4c, Ndufb4b, Ndufv3, Ndufa9, Ndufc1, Ndufs5, Ndufb4, Ndufa12, Ndufa11, and Ndufb1." (PMID 41294802, 2025).
NDUFB4 also shares sentences with these, for which no sentence is quoted: Parkinson’s (2 papers); brain diseases (1); Cognitive impairment (1); gastric cancer (1); hematological disease (1); Huntington disease (1); neurological diseases (1).